IL2 (interleukin 2)
Diseases named in the same sentence as IL2 in open-access papers (continued):
Sharing a sentence is not in itself a finding about the gene and the disease.
COVID-19 (continued). "In most studies, compared with healthy controls, COVID-19 patients had significantly higher levels of interleukin (IL)-2, IL-4, IL-6, IL-10, tumor necrosis factor (TNF)-α, and C-reactive protein (CRP) and lower lymphocyte counts." (PMID 35310853, 2022). "On the other hand, recombinant interleukin-2 stimulates lymphocyte recovery in patients with severe COVID-19." (PMID 36294868, 2022). "On the other hand, Rapamycin is widely used as inhibitor of protein synthesis and constrains the expression of pro-inflammatory cytokines such as IL-2, IL-6 and, IL-10116, therefore it has been also given for COVID-19 treatment." (PMID 35277538, 2022). "Time-adjusted differences in serum neopterin, β2M, TNF-α, IFN-γ, IL-4, and IL-2 were seen between the groups of patients with COVID-19, with higher concentrations found in neurosymptomatic patients." (PMID 35604688, 2022). "In contrast, COVID-19 ICU patients showed higher median levels of IL-2 (p < 0.001) and IL-5 (p < 0.01) by PBMCs." (PMID 36363785, 2022). "In response to polyclonal in vitro stimulation, the percentage of CD3+CD4+IL-2+ T cells showed a significant 4-fold decrease in the group that during the follow-up developed severe COVID-19 compared to participants experiencing mild symptoms (P = 0.0085)." (PMID 35860236, 2022). "This viremia and virus replication results in serious symptoms, one of which is the triggering of cytokine storms, including interferon-alpha, IL-2, IL-6, IL-10, and C-reactive protein, which can erode the health of COVID-19 patients." (PMID 35812166, 2022). "Patients experiencing COVID-19 moderate also displayed a high percentage of IFN-γ+IL-2+ within CD4+ T cells." (PMID 35887351, 2022). "Among COVID-19 patients, the most common disorders of cytokines and chemokines are increased levels of IL-1β, IL-2, IL-6, interleukin-7 (IL-7), IL-10, TNF-α, CRP, chemokine ligand 2 (CCL2), as well as an increase or decrease in the concentration of IFN-γ." (PMID 36294388, 2022). "Our results are important because it was possible to identify differences in cytokine synthesis and identify characteristic profiles in acute COVID-19 (higher levels of IL-6) and long COVID-19 (high levels of IL-2 and IL- 17)." (PMID 35846757, 2022). "Using ELISpot assay, we tested SARS-CoV-2 specific IFN-γ and IL-2-secreting T-cell responses in COVID-19 convalescents, respectively." (PMID 36283534, 2022). "We report a Human Immune System (HIS)-humanized mouse model (“DRAGA”: HLA-A2.HLA-DR4.Rag1KO.IL-2 RγcKO.NOD) for COVID-19 research." (PMID 35348437, 2022). "For instance, severe influenza differs from COVID-19 by higher levels of IL-2, APRIL, sTNF-R1, sTNF-R2, SP-D, and CXCL17." (PMID 35674675, 2022). "Representative dot-plots illustrate the comparison of CD3+CD4+ T cells expressing IL-2 in blood samples treated with polyclonal stimuli from participants who developed mild or severe COVID-19 during the follow-up." (PMID 35860236, 2022). "After PWM stimulation, COVID-19 patients showed a reduced release of IFNγ, while IL-2 levels were found similar and TNF levels were increased compared to healthy controls." (PMID 36109525, 2022). "Outbreaks of COVID-19 are accompanied by immunocompromised through hyperexpression of both proinflammatory (IL-1, IL-2, IL-6, and TNF-α) and anti-inflammatory (IL-4, IL-10, and IL-17) cytokines, and vice versa with IFN-γ." (PMID 36045713, 2022). "The levels of TNFa, IL-6, IL-1b, IFNg, IL-2, and IL-10 have been reported as inflammatory cytokines in COVID-19." (PMID 35669157, 2022). "Plasma levels of TNFα, IL-2, IL-6, IL-8, IL-10 (p < 0.001), IFNγ (p < 0.01), and GM-CSF (p < 0.05) were higher in COVID-19 patients compared to in HCs." (PMID 35625671, 2022). "For instance, the ratios of IL-2/IL-5, IL-2/IL-10, IL-2/IL-9, IL-6/IL-5, IL-6/IL-10 and IL-6/IL-9 were considerably higher in COVID-19 ICU patients as compared to HC subjects (≈8571-, 4800-, 4444-, 378-, 521-, and 172-fold differences respectively)." (PMID 36363785, 2022).
COVID-19 (continued). "Compared to patients developing mild symptoms, CD4+ and CD8+ T cell populations from COVID-19 patients admitted to intensive care units (ICU) show reduced production of IL-2, a cytokine with major functions in enhancing T and B cell proliferation." (PMID 35860236, 2022). "Based on the COVID-19 cytokine literature, we identified 6 cytokines (IL-1β, IL-2, IL-6, IL-8, IL-10, and TNF-α) commonly found in critically ill COVID-19 patients." (PMID 35033181, 2022). "COVID-19 patients have high levels of pro-inflammatory cytokines and chemokines such as IL-1β, IL-2, IL-6, IL-7, IL-10, IFN-γ, TNF-α, G-CSF, CCL2, and CXCL10." (PMID 35782361, 2022). "COVID-19 is characterized by high levels of pro-inflammatory cytokines and chemokines, including IL-2, IL-7, IL-10, G-CSF, IP10, MIP-1A, MCP-1, and TNFα, especially in patients cared for in ICU." (PMID 36423162, 2022). "Recently, in a coronavirus disease 2019 (COVID-19) study, PTL served as a herbal candidate for COVID-19 clinical evaluation by reducing cytokines, including IL-1, IL-2, IL-8, and TNF-α, and inhibiting inflammatory signaling pathways." (PMID 35514960, 2022). "In the present study, subjects in the post-COVID-19 group had higher levels of IL-17, TNF-α and IL-2 as compared to the acute COVID-19 group." (PMID 35846757, 2022). "Symptomatic COVID-19 patients had significantly (p < 0.05) higher levels of IL-10, IL-2, IL-2R, IL-6, IL-8 GM-CSF IP-10, TNF-α, IL-4, IL-5, IL-12, IFN-γ and MIP-1β compared to the asymptomatic cases." (PMID 36184636, 2022). "In this meta-analysis, we analyzed serum levels of IL-1β, IL-2, IL-4, IL-6, IL-8, and IL-10 in COVID-19 patients with different disease severities." (PMID 35540724, 2022). "The frequencies of CD4+ and CD8+ T cells producing IFN-γ, TNF-α and IL-2 in response to SARS-CoV-2 Spike peptides were measured in randomly selected COVID-19 naïve healthy adults six months after the first vaccine dose." (PMID 36389704, 2022). "We found that CD4+ cells from severe convalescent patients had significantly higher capacity to produce TNF-α, IL-2 and CD107a at time-point I, compared to healthy controls and mild/moderate COVID-19 convalescents." (PMID 35757700, 2022). "Immune cells in COVID-19 patients produce inflammatory cytokines such as IL-2 and IL-6 to stimulate B-cell proliferation." (PMID 35185890, 2022). "There is only one clinical trial investigated the administration of low-dose IL-2 in hospitalized COVID-19 patients with ARDS." (PMID 35497875, 2022). "We systematically searched records investigating the role of interleukins (IL-1β, IL-2, IL-4, IL-6, IL-8, and IL-10) in COVID-19 patients in Web of Science, Pubmed, and Embase through December 2020." (PMID 35540724, 2022). "An increased expression of the inhibitory marker NKG2A results in the decreased level of IFNγ, IL-2, TNFα, CD107a and granzyme B in COVID-19 patients." (PMID 36369012, 2022). "The ratios of IL-12/IL-4, IL-12/IL-10, IL-12/IL-5, IL-12/IL-9, IL-2/IL-10, and IL-2/IL-9 were substantially higher in COVID-19 ICU patients compared with HC subjects (≈5660-, 5333-, 2100-, 600-, 69-, and 24-fold differences, respectively)." (PMID 36363785, 2022). "The evidence also indicated that the severity of COVID-19 increases with the levels of inflammatory mediators including cytokines and chemokines such as IL-2, IL-7, IL-10, and TNF-α in the blood due to COVID-19 infection." (PMID 36091037, 2022). "Supernatants were subsequently analyzed for key inflammatory cytokines associated with the cytokine storm in COVID-19 (IFN-γ, IL-1β, IL-2, IL-4, IL-6, IL-8, IL-10, IL-12p70, IL-13, and TNF-α), using the Meso Scale platform." (PMID 36296272, 2022). "The respective IFN-γ and IL-2 ELISpots from four COVID-19 convalescents against SARS-CoV-2 spike peptides were presented, with PHA as the positive control and DMSO as the negative control." (PMID 36283534, 2022).
COVID-19 (continued). "As expected, IL-2 production significantly reduced in cytotoxic T cells from participants developing severe COVID-19 compared to those found in subjects experiencing mild disease (P = 0.0002)." (PMID 35860236, 2022). "CD8+ T cells from COVID-19 patients exerted enhanced production of IL-2, IL-17, and the expression of degranulation marker CD107a upon anti-CD3/CD28 stimulation when compared to cells from healthy controls." (PMID 36505489, 2022). "Representative dot-plots illustrate the comparison of CD3+CD8+ T cells expressing IL-2 in blood samples treated with polyclonal stimuli from participants who developed mild or severe COVID-19 during the follow-up." (PMID 35860236, 2022). "The majority of SARS-CoV-2–specific CD4+ T cells produced at least 2 cytokines, and IL-2+TNF-α+ SARS-CoV-2–specific CD4+ T cells were the dominant subpopulation of the COVID-19 immune landscape." (PMID 35230977, 2022). "NK cells also react to and generate cytokines such as IL-12 and IL-2, as well as IFNg, TNFa, and IL-6, with all these cytokines being amplified in the COVID-19 cytokine storm." (PMID 35669157, 2022). "On the other hand, a strong and specific IL-2 response has been detected in COVID-19 recovered individuals, hence this cytokine’s role in immune protection should be considered." (PMID 36079033, 2022). "These tests were used to detect interferon gamma (IFN-γ) and interleukin 2 (IL-2) secreting reactive T-cells in response to COVID-19 vaccination." (PMID 35510135, 2022). "Third, a board range of cytokines induced in patients with severe COVID-19, including IL-2, IL-7 and IL-6 family cytokines, employ JAK1 for signal transduction." (PMID 35317858, 2022). "After that, several lines of evidence confirmed that severe COVID-19 was not only related to a reduced number of circulating lymphocytes but also decreased T cell activity, especially cytokine production such as IL-2 and IFN-gamma." (PMID 35860236, 2022). "These drug schemes aim to treat and prevent COVID-19 complications but can also alter the expression of cytokines such as IL-2 and IFN-gamma and immune checkpoints as occurs with PD-1." (PMID 35860236, 2022). "The efficacy of low dose IL-2 in improving clinical course and oxygenation parameters in COVID-19 patient is now in clinical phase II trials (NCT04357444)." (PMID 34677780, 2022). "Our results agree with these conclusions; COVID-19 patients with severe illness and poor prognosis had lower levels of IL-1B, IL-2, and IL-8 than COVID-19 patients with good prognosis." (PMID 36294868, 2022). "Ours is the first study to detect ex vivo IL-2 responses, that likely correlate with central memory T cell responses, specific for cross-reactive epitopes in contacts of confirmed COVID-19 cases, early after exposure." (PMID 35013199, 2022). "In this study, we systematically analyzed the serum levels of IL-1β, IL-2, IL-4, IL-6, IL-8, and IL-10 in COVID-19 patients with different disease severities, as well as in healthy controls." (PMID 35540724, 2022). "Increased serum IL-2 levels have been detected in many patients with severe COVID-19 compared to subjects with mild disease." (PMID 36363785, 2022). "Compared with respiratory cancer patients, COVID-19 patients had lower levels of IL-2 and higher levels of CD3+CD4+ T cells and CD19+ B cells." (PMID 34712741, 2021). "The other identified biochanin A targeted gene IL2 is an important cytokine that regulates the activities of leukocytes, and it was reported to be elevated in patients with COVID-19." (PMID 34931923, 2021). "On the other hand, we have demonstrated that the IL-2/INFγ ratio, as a more reliable marker of T cell activity, was significantly higher in the COVID-19 patients with fatal outcomes (p < 0.001)." (PMID 34071149, 2021).
COVID-19 (continued). "There is likely space for investigating the possible beneficial effect of immunosuppressant CsA therapy in COVID-19, since this molecule is known to reduce IL-2 production that contributes to the cytokine storm reported in the severe forms of COVID-19." (PMID 34552938, 2021). "Studies have shown a strong correlation between the severity of COVID-19 and concentrations of different cytokines, such as IL2, IL7, IL10, GCSF, MCP1, and TNF-alpha." (PMID 33796097, 2021). "Severe COVID-19 patients show increased levels of the granulocyte colony-stimulating factor (G-CSF), IL-2, IL-6, IL-10, monocyte chemo-attractant peptide (MCP)-1), macrophage inflammatory protein 1α (MIP1α) and TNF-α." (PMID 33927728, 2021). "It was recently shown that the total number of CD4+ T cells, CD8+ T cells, B cells, and NK cells in patients was markedly decreased in the most severe forms of COVID-19 and that there is an increase of IL-2, IL-6, IL-10, and IFN-γ." (PMID 34552938, 2021). "Previous studies have found an association between an increase in levels of IL-2, IL-6, IL-7, IL-10 and TNF-α and the severity or mortality of COVID-19." (PMID 34490065, 2021). "Many inflammatory biomarkers, such as interleukin (IL)-2, IL-6, IL-10 and tumor necrosis factor, were found higher in COVID-19 patients with severe disease, compared with those with mild or moderate disease." (PMID 34640618, 2021). "The main difference in post COVID-19 versus unexposed HC were observed in IFNγ+TNFα+IL-2+ tp activated CD4+ T cells." (PMID 34322120, 2021). "The levels of IL-2 were higher in the COVID-19 patients who died, but due to very low values (within normal ranges), probably with no clinical significance." (PMID 34071149, 2021). "Evaluation of cytokines at week 2 revealed that the levels of IL-4, IL-6, IL-10, and IFN-γ were higher, while the levels of IL-2 were lower in COVID-19 patients than that in HC." (PMID 33390771, 2021). "Patients with severe COVID-19 show extreme cytokine storms involving the overexpression of IL-2 and IL-6." (PMID 33445583, 2021). "Both post COVID-19 groups had significantly higher dp TNFα+ IL-2+ SARS-CoV-2 S N-term reactive CD4+ T cells compared to HC (Ab−: p = 0.04; Ab+ p = 0.05)." (PMID 34322120, 2021). "PIMS-TS children had significantly elevated levels of cytokines, IFNγ, IL-2, TNFα, IL-1α, IFNα, IFNβ, IL-6, IL-17A, GM-CSF, IL-10, IL-33 and IL-Ra in comparison to COVID-19, seropositive and control children." (PMID 33813138, 2021). "Through the Mann-Whitney test, we found that only the average concentrations of IL-2 were higher in healthy controls than in COVID-19 patients (P<0.001)." (PMID 34489974, 2021). "IL-2 was the optimal indicator to differentiate between the COVID-19 and cancer-related immune disorder." (PMID 34712741, 2021). "In COVID-19 patients, the pro-inflammatory cytokines like IL-1, IL-2, IL-6, IL-7, IL-10, IP-10, and TNFα as well as chemokines like IL-8 are found in higher concentrations." (PMID 33981235, 2021). "Second, a score for the Severe COVID-19 patients was defined as S2 = (IL-6+sCD40L/1000 + VEGF/10 + 10*IL-10)/(IL-2 + IL-8)." (PMID 34262570, 2021). "We performed an early, longitudinal study of S1-, M- and N-specific IFN-γ and IL-2 T cell immunity and anti-S total and neutralizing antibodies in 88 mild, moderate or severe acute COVID-19 patients." (PMID 34962970, 2021). "In summary, severely affected COVID-19 patients show a continued immune reaction with egress of plasmablasts and plasma cells into the blood, which initially is controlled by IFNs, IL-2, and TGF-β, and later on predominantly by TGF-β." (PMID 33785765, 2021). "A cell signaling study in COVID-19 suggested that the JAK/STAT signaling pathway is one of the major pathways controlling IL2." (PMID 34931923, 2021). "In contrast, COVID-19 was distinguished by a lymphocyte T cytokine response, as reflected by an increase in IL-2, IL-4, IL-5, IL-7, IL-13, IL-17, and soluble CD40L (sCD40L)." (PMID 35111777, 2021).
COVID-19 (continued). "Most patients with severe COVID-19 exhibited large amounts of pro-inflammatory cytokines and chemokines, such as IL-2, IL-6, IL-7, TNF-α, granulocyte colony stimulating factor (GCSF), CXC-chemokine ligand 10 (CXCL10), CC-chemokine ligand 2 (CCL2), and CCL3." (PMID 33987176, 2021). "Our biomarker findings are similar to previously reported associations of the levels of several cytokines (e.g., IL-1ra, IL-2, IL-6, IL-8, IL-10, and IP-10) with COVID-19 severity and mortality." (PMID 34386533, 2021). "Secondly, we demonstrated profound dysfunction of T lymphocytes and NK cells in critically ill COVID-19 patients with diminished secretion of key cytokines such as IL-2, INFγ, and TNFα." (PMID 34071149, 2021). "Relative to healthy controls, low levels of IL-4, IL-1RA, GRO and VEGF, and high levels of IL-2 in nasal lining fluid, were confined to PCR-confirmed COVID-19 and PCR−/IgG+ SARI participants." (PMID 34117221, 2021). "To interrogate the potential role of T cell activation–related biomarkers in COVID-19 immunopathogenesis, we measured levels of IL-2, sCD25 (or sIL-2Rα), soluble CD40 ligand (sCD40LG), soluble FAS ligand (sFASLG), IL-7, and IL-3." (PMID 33232303, 2021). "The T lymphocytes and natural killer (NK) cells profiles were described, assessing the levels of IL-2, TNFα, and INFγ in the peripheral blood in both of the studied groups of patients with COVID-19." (PMID 34071149, 2021). "In a meta-analysis, serum levels of interleukin-2 (IL-2), IL-2R, IL-4, IL-6, IL-8, IL-10, tumor necrosis factor-alpha (TNF-α), and interferon-gamma (INF-γ) were found to be associated with severe COVID-19 cases." (PMID 34855834, 2021). "The IL-2/INFγ ratio was significantly higher in the critically ill COVID-19 patients (p < 0.001 and p = 0.007, respectively)." (PMID 34071149, 2021). "Signature cytokines in severe COVID-19 include enhanced expression of IL-6, IL-1β, IL-1α, IL-2, IL-7, IL-10, TNFα, MIP1α, MCP1, G-CSF, IFNγ." (PMID 34198973, 2021). "Soluble CD25/IL-2Rα was also increased 1.8-fold in patients with severe and critical (p<0.001) COVID-19, regarding mild COVID-19, whereas the amount of IL-2 in plasma was reduced 1.5-fold (p<0.05 for critical COVID-19)." (PMID 34122423, 2021). "Meanwhile, increased serum levels of IL-2, TNF-α, IL-7, granulocyte-colony stimulating factor and interferon-γ inducible protein 10 (CXCL10) are associated with COVID-19 disease severity." (PMID 33581688, 2021). "Our study showed that there was a good correlation between IL-2 and IL-4 in patients with COVID-19 or cancers." (PMID 34712741, 2021). "It was recently reported that in patients with severe COVID-19 the levels of IL-2, IL-7, IL-10, GSCF, IP10, MCP-1, MIP1A, and TNF-α are dramatically elevated." (PMID 34361736, 2021). "Conversely, the frequencies of CD4+ effector cells differed: the amount of specific AIM+IFNγ+ and AIM+IFNγ+IL-2+TNFα+ (triple+) CD4+ T cells were lower in COVID-19-naive older participants than in COVID-19-naive young adults." (PMID 34868051, 2021). "Lymphocyte count was negatively associated with IFNγ, IL-2, TNFα, IL-1α, IFNβ, IL-6, IL-17A, IL-10, CXCL-10 and VEGF in children with PIMS-TS and COVID-19." (PMID 33813138, 2021). "The cytokine levels of CXCL-10, GCSF, IL-2 and IL-6 were significantly reduced upon the discharge of severely ill COVID-19 patients." (PMID 34677394, 2021). "Susceptibility of these four major genes such as ACE2, IL-2, 7 and 10, TNF, and VEGF is associated with COVID-19." (PMID 33907373, 2021). "COVID-19 children had elevated levels of IFNγ, IL-2, TNFα, IL-1α, IFNα, IFNβ, IL-6, IL-17A and IL-10 in comparison to seropositive and/or control children." (PMID 33813138, 2021). "In the setting of a more severe COVID-19 illness, these pro-inflammatory cytokines IL-6, IL-2 and TNF-α are released resulting in a cytokine release syndrome, and trigger myocardial inflammation." (PMID 33034203, 2021).